TNF (tumor necrosis factor)
Diseases named in the same sentence as TNF in open-access papers (continued):
Sharing a sentence is not in itself a finding about the gene and the disease.
atherosclerosis (continued). "An investigation is performed to understand how TNFα functions at the molecular level in atherosclerosis." (PMID 40861271, 2025). "Moreover, TNF-α, IL-17, and IL-23 inhibitors have been associated with favorable effects on endothelial function and reduced oxidative stress, key mechanisms in the prevention of cardiovascular conditions such as atherosclerosis, peripheral artery disease, and cerebrovascular events." (PMID 40698258, 2025). "These pathways mainly include the AGE-RAGE signaling pathway in diabetic complications, apoptosis, fluid shear stress and atherosclerosis pathway, TNF signaling pathway, and IL-17 signaling pathway." (PMID 41394816, 2025). "Elevated IL-6, TNF-α, and IL-1β levels in HIVwt-infected mice support inflammation as the main mechanism behind Nef-dependent atherogenesis, consistent with the view of atherosclerosis as a chronic inflammatory disease." (PMID 40237461, 2025). "KEGG pathway analysis further demonstrated that YDC is associated with altered biological functions in pathways such as amyotrophic lateral sclerosis, lipid metabolism, atherosclerosis, Salmonella infection, and the TNF signaling pathway." (PMID 41357186, 2025). "The upregulated signaling pathways primarily converged on inflammation, including TNF, IL-17, and pathways related to inflammation and atherosclerosis, as well as shear stress and atherosclerosis." (PMID 40594772, 2025). "Excess visceral fat promotes tumorigenesis through increased insulin-like growth factor-1 (IGF-1) signaling and pro-inflammatory cytokines (IL-6, TNF-α), while also accelerating atherosclerosis and heart failure." (PMID 40227756, 2025). "Pro-inflammatory cytokines such as TNF-α and IL-6, which are elevated in arthritis, accelerate endothelial dysfunction and atherosclerosis, creating a bidirectional relationship between arthritis and cardiovascular pathologies." (PMID 41296710, 2025). "Compared to the blank group of mice, the levels of inflammatory factors IL-6 and TNF-α were significantly elevated in the ApoE−/− model group of mice with atherosclerosis." (PMID 40635740, 2025). "In contrast, the primary KEGG pathways enriched in the LDL and TG groups were predominantly related to inflammation, encompassing pathways such as Lipid and Atherosclerosis, TNF signaling, NF-kappa B signaling, and IL-17 signaling." (PMID 40443971, 2025). "Studies in experimental atherosclerosis models have shown that suppression of the TNF gene can slow disease progression, indicating a possible proatherogenic role for this cytokine." (PMID 40283183, 2025). "Future studies will incorporate pro-inflammatory preconditioning (e.g., ox-LDL or TNF-α exposure) prior to silencing to better mimic the pathological endothelial state observed in atherosclerosis." (PMID 41280941, 2025). "This chronic inflammation shares key features with atherosclerosis, where elevated cytokine levels, particularly TNF-α and IL-6, promote endothelial dysfunction, a key initial step in atherosclerosis pathophysiology." (PMID 40299461, 2025). "Tumor necrosis factor-alpha (TNF-alpha) is a central mediator of chronic inflammation and a validated therapeutic target in atherosclerosis and related cardiovascular disorders." (PMID 41341997, 2025). "TNFα promotes atherosclerosis through increased LDL transcytosis via endothelial cells, activating transcription factors nuclear factor kappa B and peroxisome proliferator-activated receptor γ (PPARγ)." (PMID 40558641, 2025). "Sustained inflammatory signaling activates pathways involving tumor necrosis factor α (TNFα), interleukin (IL)-17, and IL-23, leading to endothelial dysfunction, oxidative stress, and the advancement of atherosclerosis." (PMID 40698258, 2025). "SGLT2 inhibitors inhibit atherosclerosis by normalizing the expression of inflammation-related genes such as TNF-α, IL-6, ICAM-1, MMP2, and MMP9." (PMID 40869372, 2025).
atherosclerosis (continued). "Inflammation in PsD plays a pivotal role in exacerbating atherosclerosis and cardiometabolic diseases, with proinflammatory cytokines such as TNF, IL-1, IL-6, and IL-17 contributing to endothelial dysfunction and vascular damage." (PMID 41266905, 2025). "Following cadmium exposure, the levels of proinflammatory cytokines such as the interleukins IL-8, IL-1, and tumor necrosis factor (TNF-α) increase, which directly affects atherosclerosis." (PMID 39567405, 2025). "IL-1β, TNF-α and MCP-1 are inflammatory factors closely associated with the development of atherosclerosis." (PMID 40076117, 2025). "Atherosclerosis is considered to be an inflammatory disease in which monocytes and macrophages function and secrete proinflammatory cytokines, such as TNF‐α." (PMID 41142012, 2025). "In contrast, 35 pathways were highly expressed in the control group, such as the PI3K-Akt signaling pathway, MAPK signaling pathway, lipid and atherosclerosis, TNF signaling pathway, HIF-1 signaling pathway, and NF-kappa B signaling pathway." (PMID 40406620, 2025). "We found that the expression profile of aEC cells was significantly upregulated in pathways related to fluid shear stress, atherosclerosis, and TNF signaling pathway, while EC2_cluster showed downregulation in the muscle tissue development pathway." (PMID 40963808, 2025). "Abnormal overproduction of IL‐6, IL‐8, and TNF‐α are overlapped in almost diseases, prominently in degenerative (e.g., AD, osteoarthritis) and cardiovascular pathologies (e.g., atherosclerosis)." (PMID 41427020, 2025). "Among 62 MASLD-DEGs, functional enrichment was observed in pathways such as TNF signaling way, Lipid and atherosclerosis and Non-alcoholic fatty liver disease." (PMID 41200186, 2025). "KEGG profiling further revealed significant enrichment for TNF signaling pathway, Lipid and atherosclerosis, Non−alcoholic fatty liver disease." (PMID 41200186, 2025). "Further analysis showed that upregulated genes in fibroblasts were primarily associated with pathways like IL-17 signaling, legionellosis, lipid metabolism, atherosclerosis, TNF signaling, and antigen processing and presentation." (PMID 40616092, 2025). "Conversely, lipid and atherosclerosis as well as many inflammation- and infection-related pathways such as nuclear factor kappa B and tumor necrosis factor signaling are markedly down-regulated." (PMID 40052160, 2025). "Another mechanism that l‐Arg affects atherosclerosis is the inhibition of cellular signaling, including NF‐κB and TNF‐α pathways." (PMID 40161001, 2025). "This suggests pro-inflammatory cytokines, such as TNF-a, can be used to determine the extent of atherosclerosis and are important in the pathophysiology of pCAD." (PMID 40218291, 2025). "KEGG enrichment analysis using David revealed that these enriched pathways mainly included the IL-17 signaling pathway, TNF signaling pathway, lipid and atherosclerosis signaling pathway, and fluid shear stress signaling pathway." (PMID 40635740, 2025). "Lipid and atherosclerosis and the TNF signaling pathway are not only significantly enriched but also have many potential therapeutic targets, which are considered to be more important pathways in the mechanisms of H. cordata against NSCLC." (PMID 39440769, 2025). "KEGG pathway analysis further demonstrated involvement of these targets in key AS-associated pathways, including the PI3K-Akt signaling pathway, TNF signaling pathway, lipid and atherosclerosis, and apoptosis." (PMID 41424781, 2025). "Inflammatory response plays an important role in the progression of atherosclerosis, and TNF-α, IL-6, and IL-1β pro-inflammatory factors tend to induce the development of AS by destroying the vascular endothelium and increasing lipid deposition." (PMID 40606622, 2025). "M1 macrophages release pro-inflammatory factors like TNF-α, IL-6, and IL-1β, contributing to foam cell formation and accelerating atherosclerosis plaque development." (PMID 40276600, 2025).
atherosclerosis (continued). "B cells, T cells (including clonally expanded CD4+ cells with heightened proinflammatory and CD8+ cells with cytotoxic properties), granzyme B, TNF-α, IL-6, and TLR 2 and 4 all contributed to the inflammatory processes underlying atherosclerosis." (PMID 40046046, 2025). "Other pathways such as “TNF signaling,” “Lipid and atherosclerosis,” and “IL-17 signaling” further emphasize active immune and inflammatory responses." (PMID 39969652, 2025). "UCHL1 attenuated the activity of NF-kβ (nuclear factor kβ) induced by TNF-α (tumor necrosis factor) and increased the expression of eNOS, reducing ischemic vascular complications in atherosclerosis." (PMID 40141757, 2025). "KEGG enrichment analysis of genes with significant differential expression at the branches revealed enrichment in lipid and atherosclerosis and NF-kappa B and TNF signalling pathways in GDM cases." (PMID 40672961, 2025). "TNFα is known as a powerful pro-inflammatory cytokine that significantly contributes to the development of atherosclerosis." (PMID 40861271, 2025). "To elucidate the protective mechanism of EEPD1 knockout on endothelial cells in the context of atherosclerosis, we conducted high‐throughput RNA sequencing (RNA‐seq) across four experimental groups: siCon, siCon+TNFα, siEEPD1, and siEEPD1+TNFα." (PMID 40268512, 2025). "A previous study suggests that Fos plays a critical role in the development of atherosclerosis and it has been demonstrated that TNFα can upregulate Fos levels in vascular lesions." (PMID 40963808, 2025). "Hypomethylation of pro-inflammatory cytokines (IL-6, TNF-α) sustains inflammation, damages the vascular endothelium, and accelerates atherosclerosis." (PMID 41281553, 2025). "Pro-inflammatory cytokines, such as TNF-α and IL-1β, contribute to atherosclerosis by inducing the expression of E-selectin, intercellular adhesion molecule 1 (ICAM-1), and vascular cell adhesion molecule 1 (VCAM-1) in endothelial cells." (PMID 41155632, 2025). "It was reported that patients receiving TNF-α blockers have smaller cIMT values and slower atherosclerosis progression compared to those on conventional therapy." (PMID 40649049, 2025). "KEGG enrichment analysis revealed that BHEE’s putative targets were significantly associated with signaling pathways central to lipid metabolism and inflammation, including AGE-RAGE, PPAR, HIF-1, insulin resistance, TNF, and lipid/atherosclerosis pathways." (PMID 41304686, 2025). "Elevated levels of pro-inflammatory biomarkers, including interleukins, TNF-α, CRP, and serum amyloid A, have been consistently observed in IBD patients and are closely associated with increased atherosclerosis and heightened CV risk." (PMID 39859250, 2025). "Our study focused on pro-inflammatory cytokines, particularly IL-6, IL-2, and TNF-α, due to their involvement in the inflammatory cascade of atherosclerosis." (PMID 40265387, 2025). "For instance, exosomes released from mature dendritic cells enhance endothelial atherosclerosis and inflammation through the membrane TNF‐α‐mediated NF‐kB pathway." (PMID 39739455, 2025). "Flavonoids have been shown to inhibit the expression of pro-inflammatory cytokines, such as TNF-α and IL-6, which are crucial mediators in the inflammatory process of atherosclerosis." (PMID 39941147, 2025). "Pro-inflammatory cytokines (e.g., IL-1β, TNF-α) and growth factors released by activated neutrophils and platelets can promote endothelial dysfunction, atherosclerosis and cardiac remodeling." (PMID 41348675, 2025). "Adipose tissue-derived cytokines, including TNF-α and IL-6, promote oxidative stress and endothelial dysfunction, key drivers of atherosclerosis." (PMID 41299285, 2025). "The inflammatory mediators secreted by these mutant cells such as IL- 6 and TNF-α contribute to endothelial dysfunction, plaque instability, and progression of atherosclerosis, making CHIP a critical factor in the disease’s pathogenesis." (PMID 40407975, 2025).
atherosclerosis (continued). "Although TNFβ shares structural similarities with the major pro-inflammatory and atherogenic cytokine TNFα, their biological effects differ, and the role of TNFβ in atherosclerosis remains controversial." (PMID 40003949, 2025). "These potential therapeutic targets played a therapeutic role mainly by regulating lipid and atherosclerosis, the TNF signaling pathway, the IL-17 signaling pathway, and others." (PMID 39440769, 2025). "Omega-3 fatty acids have been shown to reduce plasma levels of inflammatory markers, including tumor necrosis factor-alpha (TNF-α), a cytokine implicated in the pathogenesis of atherosclerosis and other inflammatory diseases." (PMID 40427653, 2025). "Five pathways were closely related to low-salinity stress response, including Pathways in cancer (map05200), Lipid and atherosclerosis (map05417), Apoptosis (map04210), NF-kappa B signaling (map04064), and TNF signaling (map04668)." (PMID 40723320, 2025). "KEGG analysis of differential peaks in each dataset (except PU.1) highlighted relevant overlapping terms including JAK-STAT, MAPK and TNF signaling pathways and lipid and atherosclerosis." (PMID 40607379, 2025). "In the model group, levels of TNF-α and IL-6 were elevated but significantly reduced by hesperidin treatment, indicating its anti-inflammatory role in attenuating atherosclerosis." (PMID 41154096, 2025). "KEGG analysis further demonstrated significant enrichment of key targets in pathways associated with hepatitis B, antifolate resistance, lipid and atherosclerosis, as well as IL-17 and TNF-α signaling." (PMID 40630478, 2025). "MTX inhibits pro-atherosclerotic cytokines like TNF-α, IL-1, and IL-6, reducing systemic inflammation, which helps mitigate endothelial dysfunction and atherosclerosis progression." (PMID 40376321, 2025). "Since it also raises many pro-inflammatory cytokines, including interleukin (IL)−6, IL-8, IL-1β, and tumor necrosis factor-alpha, atherosclerosis is hyperactivated by such an inflammatory response." (PMID 41204397, 2025). "Secondly, TCAs suppress cytokine production, including pro-inflammatory cytokines such as TNF-α, IL-1β, and IL-6, which are key mediators in the pathogenesis of atherosclerosis." (PMID 40006011, 2025). "TNF signalling, HIF-1 signalling, and adipocytokine signalling were closely associated with fluid shear-stress-mediated atherosclerosis." (PMID 40427439, 2025). "Originally identified as “cachectin”, TNF-alpha was later recognized as a key mediator of endothelial dysfunction and plaque progression in atherosclerosis." (PMID 41341997, 2025). "Key search terms used included “atherosclerosis”, “inflammation”, “biological therapy”, “IL-1β inhibitors”, “IL-6 inhibitors”, and “TNF-α inhibitors”." (PMID 40727466, 2025). "In atherosclerosis and heart failure, endothelial dysfunction and plaque progression are driven by inflammatory cytokines (TNF-α, IL-6, CRP, etc.)and reactive oxygen species (ROS)." (PMID 41462689, 2025). "TNFα is frequently employed to stimulate cellular inflammation in order to establish an inflammatory cell model of atherosclerosis." (PMID 40861271, 2025). "l‐Arg has been extensively studied for its diverse mechanisms of inhibiting NF‐κB and TNF‐α, making it a promising treatment option for conditions that require the suppression of these pathways, including atherosclerosis." (PMID 40161001, 2025). "TPOAb, as observed in our correlation analyses, activates Th1 cells and promotes the release of pro-inflammatory cytokines (e.g., IFN-γ, TNF-α), accelerating atherosclerosis by inducing vascular inflammation." (PMID 41040864, 2025). "Experimental results showed that the IL-6 level in the galangin-treated group decreased from 9.64 to 5.42 mg/L, and TNF-α decreased from 6.63 to 3.57 mg/L in the atherosclerosis model." (PMID 40242436, 2025).
atherosclerosis (continued). "Thereafter many cells and cytokines are involved in this process, including macrophages, endothelial cells, interleukin (IL), tumor necrosis factor (TNF-α), which further induce apoptosis of smooth muscle cells and promote the progression of atherosclerosis." (PMID 40606622, 2025). "Elevated levels of inflammatory mediators, such as TNF-α and IL-6, further damage endothelial function and accelerate the progression of atherosclerosis." (PMID 40672456, 2025). "Human studies indicate that people with atherosclerosis exhibit higher serum levels of TNFα, and the concentration of TNFα in unstable atherosclerotic plaques is notably greater than in those with stable plaques." (PMID 40861271, 2025). "In the inflammatory response, the levels of inflammatory cytokines IL-1β, IL-6, and TNF-α were significantly elevated in the atherosclerosis group of rats, while paeoniflorin treatment significantly reduced the expression of these inflammatory cytokines." (PMID 40242436, 2025). "Elevated levels of proinflammatory cytokines like TNF-α, IL-6, and IL-1 contribute to endothelial dysfunction, oxidative stress, and the development of atherosclerosis." (PMID 40376321, 2025). "First, visceral fat is metabolically active and secretes large amounts of inflammatory factors such as TNF-α and IL-6, which induce chronic inflammation and accelerate the progression of atherosclerosis." (PMID 40013161, 2025). "As expected, doxorubicin induced mitochondrial dysfunction, activation of NF-κB, and upregulation of proinflammatory cytokines (e.g., IL-6, IL-1β, and TNF-α) in HUVECs, triggering EndMT, a crucial process in the initiation and progression of atherosclerosis." (PMID 39851526, 2025). "KEGG pathway analysis identified 157 relevant pathways, including the lipid and atherosclerosis, TNF signaling, IL-17 signaling, and the AGE–RAGE signaling pathways in diabetic complications." (PMID 41150817, 2025). "The genes were predominantly enriched in apoptosis-related pathways, NF-kappa B signaling, TNF signaling, necroptosis, lipid metabolism and atherosclerosis." (PMID 40870378, 2025). "Pro-inflammatory cytokines, such as IL-1β, IL-6, TNF-α, and IFN-γ, are crucial in the inflammation associated with atherosclerosis." (PMID 39941424, 2025). "In atherosclerosis, THSD1 expression is downregulated by pro-atherogenic factors such as TNFα and upregulated by the anti-atherogenic cytokine IL-10, suggesting a dynamic regulatory role in atherosclerosis prevention." (PMID 40564011, 2025). "TNF-α is a pro-inflammatory cytokine with pleiotropic effects on immune cells, participating in the inflammatory response in atherosclerosis." (PMID 40243563, 2025). "This modification was effective in assays related to the early stages of atherosclerosis, indicating IL-1β had more pronounced effects on the monocyte adhesion and migration assays than TNF-α, especially at low concentrations." (PMID 41424804, 2025). "Activation of neutrophils and the release of inflammatory mediators such as TNF-α and interleukin-6 (IL-6) contribute to vascular endothelial injury, exacerbate vascular dysfunction, and promote atherosclerosis." (PMID 41048521, 2025). "Neutrophils have been shown to play a pivotal role in the inflammatory response of atherosclerosis by secreting substantial amounts of inflammatory mediators, such as IL-1, IL-6, TNF-α, and oxygen free radicals." (PMID 41383228, 2025). "Chronic inflammation mediated by the Th17/IL-23/IL-17 axis promotes endothelial dysfunction and accelerates atherosclerosis through elevated levels of TNF-α, IL-17, and IL-6, which enhance vascular endothelial activation and plaque instability." (PMID 40777007, 2025). "Exosomes activate endothelial cell inflammation and promote the progression of atherosclerosis via TNF-α-mediated NF-κB signaling." (PMID 40642081, 2025).